CD44 (CD44 molecule (IN blood group))
Diseases named in the same sentence as CD44 in open-access papers (continued):
Sharing a sentence is not in itself a finding about the gene and the disease.
cancer (continued). "Expression of ALDH1A1, ALPL, ITGA6, CD44, PROM1 (CD133), LGR5, and YAP1 upregulated in the E2 and E3 phenotypes was consistent with cancer hallmarks including cell plasticity, self-renewal, and drug-tolerant persistence." (PMID 38915538, 2024). "The interaction between HA and CD44 promotes antiapoptotic pathways induced by receptor tyrosine kinase (RTK) activation, enhances transporter activities, and confers cancer stem cells (CSCs) with resistance to oxidative stress." (PMID 37953485, 2024). "In CRC, several cancer stem cell-specific markers have been identified, including leucine-rich repeat-containing G protein-coupled receptor 5, CD133, and CD44." (PMID 38672639, 2024). "In conclusion, we examined the associations of several reproductive variables with the expression of stem cell markers CD44, CD24, and ALDH1A1 in cancer-free women." (PMID 38577336, 2024). "In the T47D cell line, the three control samples exhibited an average expression of 10.5% of CD44 + /CD24-, which are markers commonly found in cancer stem cells (CSCs), within the total cell population." (PMID 38744871, 2024). "CD147 is a hub Ag that binds to other proteins (Intergrin, Hyaluronan, CD44, P‐gp/ABCB1, ABCG2, MCT‐1/4, CypA/B, and Gasdermin D) to drive the malignancy of cancer cells." (PMID 38469549, 2024). "Intriguingly, we also found that the cancer stem cells (CSC) score, calculated using common CSC markers (EPCAM, CD24, KRT19, SOX9, PROM1, CD44, THY1, CD47), was significantly higher in the EMT-subtype." (PMID 39095854, 2024). "A positive relationship between CD44 and micro-vessel density (MVD) has been evident in certain cancers." (PMID 38791985, 2024). "This subpopulation demonstrated high expression levels of the cancer stem cell markers POU5F1 and CD44 (POU5F1hiCD44hiE.T), with the transcription factor POU5F1 regulating the expression of SPP1." (PMID 38191424, 2024). "Cell surface CD44 and subsequently assembled HA/VCAN aggregates can assist cancer cells in establishing polarised pericellular sheaths, thereby augmenting their motility." (PMID 38791985, 2024). "Since these studies were performed in cancer cell lines, it would be interesting to test what genes the CD44ICD promotes in CD44+ astrocytes." (PMID 38247821, 2024). "It is well-appreciated that CD44 is an important prognostic marker for CSCs and is one of the most widely recognizable CSC markers across cancer types." (PMID 38612911, 2024). "Currently, the sorting of CSCs mainly depends on stem cell surface markers in different cancer cells, such as CD133, CD44, and so on." (PMID 39457544, 2024). "Within the clinical practice and oncology research, several clinically established cancer stem cell markers exist, including CD24, CD44, CD133, ALDH1, and EpCAM." (PMID 39435289, 2024). "SPP1 facilitated cancer cell chemoresistance by activating the CD44 receptor, and anti-SPP1 and anti-CD44 antibodies improved cancer cell sensitivity to cisplatin in a mouse model." (PMID 38521868, 2024). "Inspired by these reports, in this study, we used CD44+/CD24− markers to isolate CSCs and studied the role of miR-204 in several cancer hallmarks related to the stemness phenotype." (PMID 38392969, 2024). "One of the most common uses of CD44 in the cancer field is with CD24 as cell-surface markers of breast and other cancer stem cells." (PMID 38539529, 2024). "Downstream, CD44 can activate Ras‐ERKs and PI3K‐AKT pathways, influencing cancer cell proliferation and motility." (PMID 38982317, 2024). "The main ligand for CD44 is hyaluronic acid (HA), an abundant component of the extracellular matrix (ECM) expressed by stromal and cancer cells." (PMID 37754116, 2023). "Then, we evaluated the expression of c-Myc, CD44, CD24, CD133, and ALDH1A1 of sixty primary cancers and paired lymph nodes with cancer evasion." (PMID 37353799, 2023). "CSPG4, CD36, CD44 and GD2 were already shown to be involved in cancer cell migration and/or proliferation." (PMID 37803478, 2023).
cancer (continued). "As putative CSC properties play a crucial role in cancer progression, we first analyzed the expression of the pancreatic CSC markers CD44, CD24, CD133, and c-Met." (PMID 37537633, 2023). "Several known markers for many cancers’ CSCs include CXCR4, CD133, CD24, CD44, and the internal SOX2 and NANOG proteins used to evaluate stemness." (PMID 36831112, 2023). "The inherent affinity of HA toward cell surface receptors, such as CD44 and RHAMM, allows HA nanogels to selectively target cancer cells that overexpress these receptors." (PMID 38140012, 2023). "This led to an increase in the population of CD44+/high/CD24−/low cells, resulting in a significantly greater mammosphere-forming ability and increased drug resistance related to the biology of cancer stem cells (CSCs)." (PMID 37368660, 2023). "Cobalt chloride (CoCl2)-induced polyploid giant cancer cells (PGCC) exhibit the same characteristics as cancer stem cells (CSC) and express markers related to CSC (CD133 and CD44)." (PMID 37434173, 2023). "We used fluorescence activated cell sorting (FACS) to analyze the population of CSCs using CD44, EpCam, and CD133 sorting as triple markers of cancer stem-like cells." (PMID 37231419, 2023). "The combinational therapy was found to target cancer stem cells, as suggested by the reduction of cancer stemness factors, such as DCLK-1, CD24, Lgr5, CD29, and CD44, and the colonosphere formation." (PMID 36765950, 2023). "CD44 and CD24 are the “original” markers used to characterize cancer stem cells (CSCs) in breast cancer." (PMID 37709737, 2023). "As a result, the miR-5088-5p inhibitor decreased in IR-induced sphere formation ability by reducing cancer stem-like cell (CSC) marker proteins, such as Oct4, Nanog, Sox2, CD133, and CD44." (PMID 36632615, 2023). "In order to confirm the accuracy of the PCR array analysis and explore the role and correlation of CD44 and SLC7A11 in human CRC, population gene expression and survival analysis were performed using the pan-cancer data analysis tools GEPIA and ProGgene V2." (PMID 36672372, 2023). "Surviving cancer cells that managed to escape the cytotoxic effects of GEM or 5‐FU were investigated for the expression of four CSC markers: ALDH1A1, PON1, CD44, and EpCAM." (PMID 36400567, 2023). "To efficiently capture these plasma ofCS glycans, we optimized an ELISA assay with different capture and detection pairs (anti- CD44, -CSPG4, -SDC1, and rVAR2), and tested their performance of detection ofCSPGs in plasma of malignant tumor patients." (PMID 36746966, 2023). "So far, several stemness markers, such as CD44, CD24, and CD133, have been used to identify cancer stem cells in pre-clinical models." (PMID 37443350, 2023). "Overall, our results suggest that SOX (4a) targets CD-44, EGFR, AKR1D1, and HER-2 and induces ROS generation in cancer cells." (PMID 37108498, 2023). "We tested protein expression for ZEB1 and the mesenchymal cancer cell proteins MMP2, SNAI2, and CD44 due to their upregulation in GBM vs. normal tissue." (PMID 37761927, 2023). "MIF is commonly overexpressed in many cancers and, when inhibited, anti-human MIF immunoglobulins coreceptors CD74 and CD44 are also downregulated leading to a decrease in cancer cell proliferation and migration." (PMID 37514190, 2023). "Previous studies have highlighted the role of CD147 in the assembly of various pro-oncogenic proteins, including MCT4, CD44, and CD133 on the plasma membrane, emphasizing its significance in cancer biology." (PMID 37648771, 2023). "It stabilizes CD44 mRNA through binding to the CD44 mRNA 3′-UTR and promotes cell adhesion and invadopodia formation in cancer cells." (PMID 36307127, 2023). "Because laminin γ2, TSG6, and CD44 are components of ECM adhesion factors, their expression is directly connected with cancer cell migration and invasion for metastasis." (PMID 36793862, 2023).
cancer (continued). "Excess expression of Twist, Snail, TGFβ, or FOXC2 in breast cancer results in cells that are more mesenchymal and are characterized by cancer stem cell (CSC) markers, i.e., CD44+ and CD24-low." (PMID 38139368, 2023). "In agreement with the fact that EMT and chemoresistance correlate with cancer stemness, this study demonstrated the overexpression of CSC markers such as CD44 and CD133 with repeated P. gingivalis infection." (PMID 38170015, 2023). "CD44, a CSC biomarker, is involved in cancer cell proliferation, cell differentiation, cell migration, and angiogenesis." (PMID 37553567, 2023). "Common palmitoylated proteins in different cancer types are EGFR, RAS (KRAS4A, NRAS), CD82 tetraspanin, CD44, PD-L1, and CKAP4." (PMID 36671802, 2023). "Researchers have elucidated the complex regulatory relationship between EPAS1 and PI3K/AKT signaling pathway in different cancers, in which factors such as PTEN, YY1, SCD1, and CD44 also play important roles." (PMID 37124944, 2023). "Research has revealed a notable association between the manifestation of PD-L1 and CTLA-4 and the presence of cancer stem cell (CSC)-like properties, including elevated levels of CD44 and/or CD133 expression on neoplastic cells." (PMID 37368660, 2023). "Intriguingly, OTUB1 is reported to stabilize SLC7A11 through CD44, which is known to be an important CSC marker in human cancers." (PMID 37726816, 2023). "Cancer cells undergoing an epithelial-to-mesenchymal transition (EMT) acquire stem cell-like properties and show increased CD44 expression with increased invasiveness and resistance to chemotherapy." (PMID 37461792, 2023). "However, the mechanism of CD44’s involvement in cancer metastasis remains unknown." (PMID 36776876, 2023). "These nanocapsules enhanced cytotoxicity on CaCo-2 cells and reduced cancer stem cell markers in survivin, triple-positive CD133, and CD44 cancer stem-like cells." (PMID 37242604, 2023). "We previously demonstrated that TRPV2 knockdown enhances the stemness of cancer stem-like cells through increased expression levels of cancer stem cell markers ALDH1, CD133, and CD44." (PMID 37733242, 2023). "The expression of p-CDK1, p-STAT3, CD44, and Sox2 was increased by gemcitabine, while fisetin could reverse the upregulation of these proteins in the combination therapy group, suggesting that inhibition of cancer stemness-related proteins by fisetin enhanced the effects of gemcitabine." (PMID 37743465, 2023). "On the other hand, Ad-CD44-N-HIF3α4 did exert high anti-tumor activity in MDA-MB-231 tumors by targeting CD44 and HIF, both closely related to cancer stem cells." (PMID 37064130, 2023). "We therefore evaluated the expression of a panel of epithelial (KRT5, 7, 8, 18, and CDH1), mesenchymal (VIM, FN1, SNAI1, TWIST1, COL1A1, and PRRX1), and cancer stem cell (ALDH1A2, ALDH7A1, CD44, and CCND1) markers in all samples." (PMID 36980717, 2023). "Targeting c-MET activity, either with small molecule inhibitors or RNA interference, has been shown to suppress the cancer stem-like phenotype by downregulating CSC markers, including CD133, CD44, ABCG2, Sox2, and ALDH1." (PMID 38201226, 2023). "Antibodies against CD44 including bivatuzumab and RO5429083 have shown antitumor activity in patients with advanced cancers." (PMID 37092398, 2023). "In the reprogramming group, expression levels of cancer stem cell markers CD44 and CD133 significantly decreased, from 92.92% to 26.81% and from 88.51% to 16.22%, respectively; moreover, counts of CD44+ and CD133+ cells decreased from 70.20% to 12.20%." (PMID 37771785, 2023).
cancer (continued). "Independent validation by cytology (n: 133) showed that expression of SNA-1 and CD44 significantly delineate HGD and cancer with high sensitivity (>83%)." (PMID 37747904, 2023). "Levels of PGE2 were found to be correlated with cancer stem cell markers including CD133, CD44, LGR5 and SOX258." (PMID 37875589, 2023). "Second, the protein levels of CD44, CD133, CD133high, and CD44high TNBC are indicators of cancer stem cell characteristics that promote metastasis; the protein levels increased in the ICAM2-overexpressing cells compared with vector control." (PMID 37620448, 2023). "The activation of STAT3 correlated with the increased expression of ALDH1, CD44, OCT4, and SOX2 in cancer cells." (PMID 37453969, 2023). "With CD44-, CD117-and CD166-positive cancers, we found a significant effect of the expression of these markers on OS." (PMID 38188613, 2023). "We also evaluated the expression of CD44 and CD133, which are the cancer stemness markers in many cancers, including HCC." (PMID 36831279, 2023). "BR4 is the only cell culture that is characterized by the presence of all cancer stem cell markers (9.92% CD133+, 78.9% CD44+, 9.56% CD133+/CD44+, 20.4% CD15+, 1.95% CD171+)." (PMID 37998351, 2023). "In certain cancers, lactate stimulates fibroblast expression of hyaluronan and its receptor CD44, resulting in an increased ECM stiffness that favors cancer cell migration, invasion, and metastasis formation." (PMID 37444583, 2023). "Caffeic acid effectively inhibited cancer stem cells (CSC) and reduced radiation-induced sphere formation of CD133+ and CD44+ CSC in two patient-derived tumor xenograft (PDTX) models of human CRC in immune-suppressed mice." (PMID 36765950, 2023). "CD44 and CD104 have been suggested as markers for discrimination of the E, mixed/hybrid E/M and M state of cancer cells." (PMID 38139138, 2023). "Cancer stem cell markers were also examined, which showed an upregulation in ALDH1A3, CD44, and WNT5A in amoeboid cells, and increased SOX2 and BMI1 in escaping cells." (PMID 37575281, 2023). "CD44 is a transmembrane glycoprotein which binds hyaluronic acid in the ECM and is recognized as a molecular marker for cancer stem cells." (PMID 37174618, 2023). "CD44 is known to be involved in various cellular pathways, such as PI3K/AKT and Src/MAPK signaling, which contribute to cancer cell proliferation and invasion." (PMID 37669956, 2023). "Flow cytometric analysis showed that the population of POU5F1-positive cells was also detected in 2DOs as cancer cells and differed from previously reported CRC stem cell marker-positive cells, including those with the markers, CD133, CD44, CD24, and LGR521." (PMID 37996567, 2023). "Pre-treatment of CD8+ T cells with anti-CD11a antibodies (LFA-1 blockade), reduced CD69 and CD44 expressions on T cells after co-culture experiments, indicating that ICAM1 on cancer cells mediates the interaction with T cells by binding to LFA-1." (PMID 36871040, 2023). "Given its widespread expression in cancer and its essential role in promoting cell migration and invasion in GBM, CD44 holds promise as a potential therapeutic target." (PMID 37593751, 2023). "In cancer, OPN and CD44 overexpression is a marker of aggressive disease and poor prognosis, and correlates with therapy resistance." (PMID 38067149, 2023). "This study aimed to investigate the immunostaining of the putative cancer stem cells (CSC) markers ALDH1 and CD44 in AC (n=30) and LSCC (n=20)." (PMID 38126564, 2023). "The most significant cancer-related pathways regulated by asporin are FGF2, TGF-β1, BMP-2, epidermal growth factor receptor (EGFR) and CD44." (PMID 36765749, 2023). "To quantitate the plasma ofCS/ofCSPGs, we optimized an ELISA using different capture/detection pairs (rVAR2/anti-CD44, -SDC1, and -CSPG4) in a case-control study with six cancer types." (PMID 36746966, 2023).
cancer (continued). "In previous studies, it has been reported that YBX1 promoted the growth of cancer stem cell population and seemed to modulate the expression of numerous stemness genes, including SOX2, CD10, CD24, and CD44." (PMID 36805592, 2023). "Since literature evidence supports the important roles of CD44, BATF, LGALS3, and NFKBIZ in cancer, we decided to validate the expression of these genes with independent experimental methods." (PMID 36982699, 2023). "Nevertheless, CD44 also interacts with numerous other ECM molecules, growth factors and cytokines and advances tumor growth, angiogenesis, metastasis and cancer stem cell (CSC)-related properties." (PMID 36342580, 2023). "Next, we compared CD44’s predictive ability for immunotherapy efficacy to other canonical biomarker signatures in the TIDE database, using treatment responses from various cancer cohorts treated with ICB." (PMID 37117249, 2023). "The relationship between TM4SF1 and cancer stem–related molecules CD44, CD133, OCT4, and SOX2 was detected via qPCR and WB, which confirmed the decrease in the expression of CD44, CD133, OCT4, and SOX2 with the silencing of TM4SF1." (PMID 37069693, 2023). "The colocalizations of the ofCS with their core proteins (CD44, CSPG4, and SDC1) were detected on various cancer cells by immunofluorescence analysis." (PMID 36746966, 2023). "This loop promotes the acquisition of cancer stem-like properties and impedes the antitumor efficacy of gemcitabine in PAAD by activating the CCL5/CCR5/Sp1/CD44 axis." (PMID 37553567, 2023). "During cancer progression and metastasis, epithelial to mesenchymal transition (EMT) is controlled by CD44 undergoing isoform switching." (PMID 36876041, 2023). "EL001672 and 1′-O-methyl-averantin suppresses the cancer stemness markers such as ALDH1, CD44, CD133, Lgr-5, Msi-1 and EphB1." (PMID 36797277, 2023). "CAMs pre-stimulated by cancer cell–derived TGF-β secret osteopontin, which, in turn, activates CD44/PI3K/AKT pathway in OCSCs, leading to ABC transporters’ overexpression and chemoresistance." (PMID 37448521, 2023). "Sphere formation assay revealed that fisetin reduced the cancer stemness promoted by gemcitabine in human PANC-1 cells and KPC mice KPC203 cells, as well as the proportion of CD44+/CD24+ cells among PANC-1 cells, further proving the results." (PMID 37743465, 2023). "From heatmap analyses, it was observed that all of these protein-coding hub genes were up-regulated in the case of Ponatinib-resistant cancer and only FN1, CD44 and TIMP1 were up-regulated in Foretinib-resistant cancer." (PMID 35534592, 2022). "MRNA expression of SPP1, VEGFA, POSTN, CD44, FOXO1, and RUNX2 genes was significantly change with the cancer stages of the patients." (PMID 36424413, 2022). "The study identified FN1, CD44, TIMP1, SPARC and SNAI2 as common coding hub proteins for most of the drug-resistant cancer types." (PMID 35534592, 2022). "The knockdown of FOXM1 downregulated the CD44 and SOX2 CSC markers, which are involved in the emergence of CSCs in various types of cancers." (PMID 35887129, 2022). "We found that CD44, CDK6, GATA4, GATA6, KLF5, and KRAS, which were amplified in TCGA STAD cohort, were amplified in cancer cell clusters." (PMID 35087207, 2022). "This review summarizes new research on the metabolism and interactions of HA with its binding proteins, known as hyaladherins (CD44, RHAMM), revealing the molecular basis for its distinct biological function in the development of cancer." (PMID 36613567, 2022). "Collectively, our findings illustrated that MZF1-mediated miR-328-3p acted as a cancer suppressor in STAD progression via regulation of CD44, which suggested the possibility of the MZF1/miR-328-3p/CD44 axis as a novel promising therapeutic candidate for STAD." (PMID 35669102, 2022).